STAT3 (signal transducer and activator of transcription 3)
Diseases named in the same sentence as STAT3 in open-access papers (continued):
Sharing a sentence is not in itself a finding about the gene and the disease.
prostate carcinoma (continued). "Finally, the disruption of the IL6R/STAT-3 axis in prostate cancer cells and the blocking of TIGIT on NK-92 were observed to increase the cytotoxicity of NK-92 cells against DU145 cells through an increase in sFasL, granzyme A, granzyme B, and granulysin." (PMID 35465350, 2022). "The experience and disappointment with STAT3 inhibitors were also apparent for prostate cancer." (PMID 34047814, 2021). "miR-424 affects the ubiquitination and activation of STAT3 to promote prostate cancer development." (PMID 34395419, 2021). "Therefore, STAT3 is a potential target molecule for the development of therapeutic agents for prostate cancer." (PMID 34684783, 2021). "For instance, leptin stimulates prostate cancer cell proliferation and migration through STAT3." (PMID 34025420, 2021). "Inhibition of STAT-3 further results in inhibition of prostate cancer cell growth." (PMID 35069196, 2021). "Moreover, the functional studies demonstrated that ALDH expression and its activity in ALDH-positive prostate cancer cells were significantly decreased when inhibited the activation of STAT3, as well as data shown in CCA cell lines." (PMID 34837926, 2021). "We aimed to identify novel markers for aggressive prostate cancer in a STAT3-low proteomics-derived dataset of mitochondrial proteins by immunohistochemical analysis and correlation with transcriptomic data and biochemical recurrence in a STAT3 independent PCa cohort." (PMID 34885151, 2021). "Among cucurbitacin derivatives, cucurbitacin-D (CuD) showed an effective inhibitory effect on the proliferation of colon, breast, lung, cervical, and prostate cancer cell lines as a result of Janus kinase/signal transducer activator of transcription 3 (JAK/STAT3) signaling pathway inhibition." (PMID 33525658, 2021). "Importantly, however, our findings establish that MSC-selected apoptosis resistant F2 prostate cancer cells are highly sensitive to STAT3 inhibition in vivo." (PMID 33526787, 2021). "STAT-3 is also expressed and phosphorylated in metastatic lesions of prostate cancer." (PMID 34204596, 2021). "In addition, AGTR1 has been identified to be the upstream molecule of MEK/ERK/STAT3 pathway in regulating the growth and metastasis of prostate cancer." (PMID 34496800, 2021). "Thus, bone marrow MSCs drive the emergence of therapy-resistant bone metastatic prostate cancer yet this can be disabled by targeting STAT3." (PMID 33526787, 2021). "Notably, STAT3 ablation or inhibition impairs MSC-selected prostate cancer cell growth and survival." (PMID 33526787, 2021). "Inhibition of multiple pathways, including those of AR and STAT-3 in prostate cancer, could be achieved by treatment with galiellalactone." (PMID 34204596, 2021). "Synergistic activity of anti-STAT3 inhibitors on tumor microenvironment might be more important than their direct cytotoxic effect on prostate cancer cells." (PMID 34067832, 2021). "Additionally, decreased AR expression induced stemness phenotypes in prostate cancer cells through STAT3 activation." (PMID 34226586, 2021). "STATs are transcription factors that play an important role in the process of inflammation, and STAT3 is highly expressed and may be related to the progression of many types of cancer, including prostate cancer." (PMID 34295247, 2021). "STAT3 is an established target in the majority of advanced human tumors including prostate cancers." (PMID 34067832, 2021). "Therefore, piperine via PARP-1 cleavage, inhibition of NF-κB, downregulation of STAT-3, and activation of caspase-3 can inhibit prostate cancer and cell proliferation." (PMID 35069196, 2021).
prostate carcinoma (continued). "Interleukin‐6 induces cell growth of prostate cancer by activating STAT3 signalling pathway." (PMID 33094561, 2020). "Here we investigated the effect of galiellalactone (GL), a direct STAT3 inhibitor, on CSCs derived from prostate cancer patients, on docetaxel-resistant spheres with stem cell characteristics, on CSCs obtained from the DU145 cell line in vitro and on DU145 tumors in vivo." (PMID 32811873, 2020). "Notably, the significant positive correlations between CCL5 and PCSCs-related proteins including ALDH1A1 (p = 0.0001) and STAT3 (p = 0.0001) were observed in the samples of human prostate cancer tissue microarray." (PMID 32300100, 2020). "However, the medium staining of STAT3 was found in normal prostate tissues and high staining in prostate cancer, suggesting that the STAT3 protein expression was higher in prostate cancer than normal tissue." (PMID 32486001, 2020). "IL6/JAK/STAT3 axis is known to drive proliferation in prostate cancer cells." (PMID 33284790, 2020). "The activity of the transcription element STAT3 is frequently altered in prostate cancer cells." (PMID 32100392, 2020). "Furthermore, ST3-H2A2 (LDTRYLEQLHKLY) bound to both phosphorylated and unphosphorylated STAT3 in prostate cancer cells, decreased STAT3 DNA binding ability and induced apoptotic cell death." (PMID 32872659, 2020). "Likewise, STAT3 was activated in LNCaP cells cultured with CAF-conditioned medium or conditioned medium of normal fibroblasts from prostate cancer patients (NF-CM)." (PMID 32528731, 2020). "CCL5 could significantly promote STAT3 expression, phosphorylation as well as its nuclear translocation in both DU145 and PC3 cells, indicating that CCL5 could induce persistent activation of STAT3 signaling in prostate cancer cells." (PMID 32300100, 2020). "In addition, we show that targeting STAT3 augments oncolytic NDV‐elicited expression of ICD markers in prostate cancer cells." (PMID 32100392, 2020). "Furthermore, we demonstrate that targeting signal transducer and activator of transcription 3 (STAT3) enhances the induction of ICD in prostate cancer cells upon NDV infection." (PMID 32100392, 2020). "In addition, the tumorigenicity of cancer stem cells was found to be promoted by EZH2 via the binding and methylation of STAT3 in glioblastoma and in a model of prostate cancer." (PMID 33163485, 2020). "RNA-sequencing and mechanistic explorations further revealed that CCL5 could promote PCSCs self-renewal and prostate cancer metastasis via activating the β-catenin/STAT3 signaling." (PMID 32300100, 2020). "Taken together, TAMs/CCL5 could promote PCSCs self-renewal and prostate cancer metastasis via activating β-catenin/STAT3 signaling." (PMID 32300100, 2020). "In response to oxidative stress induced by tert-butyl hydroperoxide treatment in prostate cancer cells, S-glutathionylation of STAT3 prevents STAT3 phosphorylation at Tyr705 and inhibits the formation of STAT3 dimers, which precludes STAT3 canonical transcriptional activity." (PMID 33003453, 2020). "Hsp27 is required for IL-6-mediated EMT via STAT3/Twist signaling in prostate cancer." (PMID 32315283, 2020). "Additionally, the SOX1 gene interferes with the STAT3 signaling pathway and regulates prostate cancer stem cell invasion." (PMID 32675943, 2020). "Therefore, STAT3 plays a major role in the occurrence and development of prostate cancer by effectively blocking the activation of related pathways, which is a novel method of cancer treatment." (PMID 32784629, 2020). "In addition, we here found that inhibition of STAT3 enhances oncolytic NDV‐induced cell death in prostate cancer cells." (PMID 32100392, 2020). "Constitutive activation of STAT3 has been connected to prostate cancer malignancy, and abolishing the STAT3 activity may diminish tumor growth and metastasis." (PMID 32349303, 2020).
prostate carcinoma (continued). "Our data also suggest that a combination of inhibition of STAT3 with oncolytic NDV could boost NDV‐based anti‐tumour effects against prostate cancer." (PMID 32100392, 2020). "In Pten-deficient model mice for prostate cancer, a high-fat diet mediated inflammation-induced M2 TAM differentiation and expansion of MDSCs, accelerated IL-6 secretion, and facilitated tumor growth via IL-6/STAT3 signaling pathway." (PMID 32824865, 2020). "Inhibition of mitoSTAT3 leads to aggregation of STAT3 protein and death of prostate cancer cells." (PMID 33257655, 2020). "Moreover, CDK5 is also a positive regulator to cell proliferation through STAT3 activation and STAT3-mediated androgen receptor (AR) activation via the phosphorylation of STAT3 at Ser727 in prostate cancer." (PMID 33396266, 2020). "In summary, the present study demonstrates that TAMs-secreted CCL5 could promote PCSCs self-renewal and prostate cancer metastasis via activating β-catenin/STAT3 signaling." (PMID 32300100, 2020). "Agarwal and colleagues have also found that the combination of the Jak1 inhibitor and silibinin (an active constituent of silymarin) is able to reduce STAT3 phosphorylation and to activate caspase-9 and caspase-3, thus leading to the apoptosis of prostate cancer DU145 cells." (PMID 33299414, 2020). "When STAT3 was specifically turned off in myeloid cells expressing TLR9 from prostate cancer patients, using a CpG-STAT3 siRNA or CpG-STAT3 antisense oligonucleotides, it abrogated the immunosuppressive effects of patient-derived MDSCs on effector CD8+ T-cells." (PMID 31480382, 2019). "Importantly, in recent years antibodies (e.g., siltuximab) targeting the IL-6/JAK/STAT3 pathway have been tested as monotherapy or in combination with cytotoxic drugs in various clinical trials for treatment of cancers, including prostate cancer." (PMID 31143708, 2019). "Based on our results, CDK5 activation promotes the growth of prostate cancer cells by direct interaction with STAT3 through Ser-727 phosphorylation, while CDK5-mediated STAT3 activation contributes to full AR transactivation in addition to CDK5-dependent Ser81-AR regulation." (PMID 31395805, 2019). "Therefore, activating IL-6/STAT3 signaling plays an important role in the induction of CD44-positive prostate cancer." (PMID 31315262, 2019). "Part of the Ca2+ signaling cascade, calmodulin kinase type II gamma (CaMKIIγ), plays an important role in tumor progression of prostate cancer by activation of AKT in a PI3K-independent manner, or in the development of colitis-associated cancer through activation of STAT3." (PMID 31861674, 2019). "This biphephonol has proven chemopreventive and/or therapeutic effects against prostate cancers, affecting multiple signaling pathways, molecular and cellular targets (e.g., NF-κB, STAT3, EGF receptor, cell survival signaling, cell cycle, cyclooxygenase, and other inflammatory mediators)." (PMID 31261861, 2019). "Similarly, in prostate carcinoma, DC generated in the presence of stromal myofibroblasts factors expressed significantly elevated levels of PD-L1 in a STAT3 and IL-6-dependent manner." (PMID 31480382, 2019). "Pre-treatment of prostate cancer cells with zerumbone significantly decreased the radiation-induced expression of phosphorylated ATM (ataxia telangiectasia-mutated) and suppressed the expression of JAK2 and STAT3, which are involved in DNA damage repair." (PMID 30781671, 2019).
prostate carcinoma (continued). "To evaluate the clinical benefits and pitfalls of current prostate cancer treatments, we will focus on two differentially activated transcription factors, one of which is part of the standard of care in prostate cancer treatment (AR), and a newly identified but promising target (STAT3)." (PMID 31771198, 2019). "Importantly, Stat3 inhibitors were highly efficient in eradicating prostate cancer in xenotransplantation models from primary prostate cancers." (PMID 31366128, 2019). "To determine whether cIAP2 is a direct transcriptional target of NF-κB or STAT3, we used the STAT3-null prostate cancer cell line PC3." (PMID 30854231, 2019). "In addition to STAT3 pathway or indirect inhibitors, various direct STAT3 inhibitors have been developed and some have been tested in prostate cancer models." (PMID 31143708, 2019). "Importantly, activation of STAT3 has been associated with promotion and maintenance of CSC, tumorigenicity and metastatic capability in prostate cancer." (PMID 31143708, 2019). "A large set of evidence reveals a critical role of the STAT3 in prostate cancer." (PMID 31143708, 2019). "In summary, prostatic epithelial AR silencing via siAR promotes STAT3 activation and EMT in prostate cancer cells via CCL2 induction, which may be associated with a secretory phenotype and pro-invasive characteristics of prostate cancer cells." (PMID 30871130, 2019). "STAT3 plays a pivotal role in progression of many tumor types, including prostate cancer tumors." (PMID 31530281, 2019). "IL-6 might increase the number of local MDSCs and promote the proliferation of prostate cancer cells via signal transducer and activator of transcription 3 (STAT3) pathways." (PMID 30736371, 2019). "Overall, these results suggest that STAT3 inhibition is a rational therapeutic approach for ENZR prostate cancer, and could be valuable in CRPC in combination with ENZ." (PMID 30470788, 2018). "Finally, pimozide also demonstrated anti-cancer activity by inhibiting STAT5 (signal transducer and activator of transcription 5) in cells and a mouse model of leukemia and STAT3 in prostate cancer cells." (PMID 29790082, 2018). "Moreover, in human prostate tumor tissues, androgen receptor down-regulation further leads to the development of prostate cancer stem-like cells, which requires STAT3 activity." (PMID 29636641, 2018). "Thus, our findings suggest that ATR II acts at least partly through inhibition of constitutively activated STAT3 and that it represents a novel candidate for prostate cancer chemotherapy drugs." (PMID 30545141, 2018). "Constitutive STAT3 activation is often displayed by various carcinomas including prostate cancer, and pharmacological drugs that can abrogate deregulated STAT3 activation may have a potential for cancer therapy." (PMID 30541589, 2018). "In prostate cancer cells and chronic myelogenous leukemia cells, the cytotoxic results indicate that heteronemin induced both the intrinsic and extrinsic pathways and cell apoptosis was mediated by Met/STAT3 pathway in prostate cancer and NF-κB pathway in chronic myelogenous leukemia cells." (PMID 29914195, 2018). "More recently, CRIF1 was seen to be highly expressed, together with STAT3, in the epithelium and stroma of prostate cancer and to compete with the coactivator p160 for the binding to the androgen receptor (AR), which is known to have a pro-tumorigenic role in this neoplasia." (PMID 29914167, 2018). "In addition, the marine natural product exhibited potent antitumor effect via the inhibition of c-Met/STAT3 pathway in prostate cancer PC3 cells." (PMID 29890785, 2018). "Recently, several reports found that the STAT3 inhibitors could effectively reduce tumor growth and metastasis in mouse models of prostate cancer." (PMID 28783760, 2017). "High levels of IL-6 expression is detected in patients with prostate cancer which could activate IL-6 receptor, leading to increased STAT3 activation." (PMID 28467474, 2017).
prostate carcinoma (continued). "Constitutive activation of STAT3 and its other family members has been detected in a variety of human tumor specimens and cancer cell lines, including prostate cancer, so there is a need for time to develop novel, improved therapeutic approaches and new therapeutic agents to cure prostate cancer." (PMID 28178219, 2017). "Finally, Capz treatment inhibited tumor growth in a xenograft prostate cancer model by inhibiting STAT3 phosphorylation and Ki-67 expression in tumor tissues." (PMID 27458171, 2017). "Here, we investigated whether capsazepine (Capz), a synthetic analogue of capsaicin, exerts anticancer effects by inhibiting STAT3 activation in prostate cancer cells." (PMID 27458171, 2017). "Moreover, cryptotanshinone can inhibit STAT3 Tyr705 phosphorylation in DU145 prostate cancer cells by binding to the SH2 domain of STAT3 and blocking the formation of STAT3 dimers." (PMID 29207614, 2017). "Together, emerging evidence suggests that targeting the CCL2/STAT3–Skp2 pathway may offer therapeutic benefits to patients with prostate cancer." (PMID 28157698, 2017). "Similarly, another study used DU145 prostate cancer cells to show that CPT inhibits constitutive STAT3 functions by blocking dimerization, but there was lack evidence in a xenograft mouse model." (PMID 28654902, 2017). "Morusin inhibited glioblastoma cell growth by regulating EGFR and DR5 to induce TRAIL sensitization both in vivo and in vitro, suppressed breast cancer cell growth via C/EBPβ- and PPARγ-mediated lipoapoptosis, and induced cell death by inactivating STAT3 signaling in prostate cancer cells." (PMID 28915664, 2017). "Furthermore, transfection of dominant-negative STAT3 plasmid or antisense STAT3 oligonucleotides inhibits STAT3 gene expression and promotes apoptosis in prostate cancer lines." (PMID 27458171, 2017). "Therefore, the potential combination of inhibiting both Ref-1/APE1 redox function and STAT3/survivin provides an avenue of targeting both the overarching regulator and downstream effector of an anti-apoptotic pathway integral to prostate cancer." (PMID 28825044, 2017). "In addition, diallyl trisulfide inhibits prostate cancer development in a transgenic mouse model, correlating with a decrease in phosphorylated Stat3." (PMID 29056905, 2017). "We then examined whether capsaicin (Caps) similarly inhibited constitutive STAT3 activation in human prostate cancer DU145 cells." (PMID 27458171, 2017). "Following earlier studies suggesting that ASC‐J9® may alter activated p‐STAT3 signals to suppress prostate cancer metastasis, here the authors found that combining Sorafenib with ASC‐J9® may synergistically suppress HCC progression." (PMID 27668844, 2017). "Activation of STAT3 signaling is essential in the metastatic progression of prostate cancer, and targeting STAT3 pathway can yield a potential therapeutic intervention for prostate cancer." (PMID 28764703, 2017). "The purpose of this study was to examine whether Capz inhibits STAT3 signaling cascades to inhibit the growth and survival of human prostate carcinoma cells." (PMID 27458171, 2017). "Moreover, STAT3 is a valuable biomarker for prognosis prediction and a therapeutic target in human solid tumors, including prostate cancer." (PMID 28157698, 2017). "Finally, intraperitoneal Capz administration decreased tumor growth in a xenograft mouse prostate cancer model and reduced p-STAT3 and Ki-67 expression." (PMID 27458171, 2017). "Other data show that there is an inverse correlation between the expression of SOCS-3 and IL-6-induced phosphorylation of STAT3 in prostate cancer cells; furthermore, downregulation of SOCS-3 by a short interfering RNA approach resulted in inhibition of proliferation and an increased apoptotic rate." (PMID 29234375, 2017). "Indeed, persistent STAT3 activation changed cellular phenotype of benign prostate cells to a malignant one in prostate cancer." (PMID 28783760, 2017).